NF2 (NF2, moesin-ezrin-radixin like (MERLIN) tumor suppressor)
Diseases named in the same sentence as NF2 in open-access papers (continued):
Sharing a sentence is not in itself a finding about the gene and the disease.
mesothelioma (155 papers, 2008 to 2026). A usually malignant and aggressive neoplasm of the mesothelium which is often associated with exposure to asbestos. "Mesothelioma is characterized by the inactivation of tumor suppressor genes, with frequent mutations in neurofibromin 2 (NF2), BRCA1-associated protein 1 (BAP1), and cyclin-dependent kinase inhibitor 2A (CDKN2A)." (PMID 40362535, 2025). "This metabolic rewiring is not merely epiphenomenal; it represents a critical dependency for the proliferation and survival of NF2-deficient mesothelioma cells." (PMID 40707701, 2025). "The reintroduction of NF2 into these cells reverses this invasive behavior, suggesting that FAK targeting is a potential therapeutic strategy for NF2-deficient mesotheliomas." (PMID 40362535, 2025). "K-975 covalently binds to the internal cysteine in the palmitate-binding pocket and suppresses proliferation in NF2-deficient mesothelioma cell lines and xenograft models." (PMID 41347094, 2025). "Our preclinical results, encompassing both commercial and primary mesothelioma models, indicate that the de novo pyrimidine biosynthesis pathway is a promising synthetic lethal target in NF2-deficient PM." (PMID 40707702, 2025). "With the activity of the candidate compounds established, we next sought to determine the in vitro anticancer potential of candidate therapeutics in the context of NF2-deficient mesothelioma." (PMID 40744733, 2025). "This work highlights a potential therapeutic strategy for targeting NF2-deficient mesothelioma through metabolic intervention." (PMID 40707702, 2025). "This is somewhat unexpected, as recent findings have indicated that NF2-deficient mesothelioma cells are more sensitive to TEAD inhibitors." (PMID 40744733, 2025). "This YAP-driven metabolic rewiring provides a potentially targetable vulnerability in NF2-deficient mesothelioma." (PMID 40707702, 2025). "Although in vitro studies assessing the efficacy of TEAD inhibition in NF2-deficient mesothelioma cells have been described, these are limited by the heterogeneous genomic and transcriptomic landscapes associated with cell lines of mixed origins." (PMID 40744733, 2025). "To identify molecular features associated with this sensitivity, we examined the mutational status of genes commonly altered in mesothelioma, including NF2, LATS1/2, and BAP1." (PMID 41463232, 2025). "VT103 and VT104 also reduced proliferation of NF2-deficiency mesothelioma xenografts in mice and in multiple NF2-mutant or NF2-deficient cell lines." (PMID 41347094, 2025). "We investigated these compounds in NF2-deficient mesothelioma NCI-H226 cells, which are highly sensitive to TEAD inhibition in cell proliferation and viability assays." (PMID 41193428, 2025). "Apart from nonsense/missense mutations or small/large deletions with loss of heterozygosity, which lead to bi-allelic loss of function, mesotheliomas can also exhibit additional structural abnormalities, such as gene rearrangement that disrupts the NF2 region." (PMID 40227645, 2025). "Together, these layers of evidence pinpoint de novo pyrimidine biogenesis as an Achilles’ heel of NF2-deficient mesothelioma." (PMID 40707701, 2025). "Inhibitors of the TEAD transcription factors have shown effectiveness in inhibiting the growth of YAP/TAZ activated tumor cells (e.g., Nf2-mutated mesothelioma cells) and are currently being tested in cancer clinical trials." (PMID 39953252, 2025). "Mesothelioma is a rare secondary tumor in brain cancer patients and the association with NF2-SWN has been described only in a few anecdotal cases and never in the pediatric field." (PMID 40725095, 2025). "Three mesothelioma cell lines were used in this assay: NCI-H2052 cells harboring NF2 mutations, Y-MESO-27 cells with LATS1/2 alterations, and NCI-H2452 cells carrying BAP1 mutations." (PMID 41463232, 2025). "Mice harboring heterozygous Nf2 mutations exhibit increased susceptibility to asbestos-induced mesothelioma than mice with wild-type Nf2." (PMID 40362535, 2025).
mesothelioma (continued). "IAG933 has entered a phase 1 trial in patients with previously treated advanced mesothelioma, NF2/LATS1/LATS2 mutated tumors, and YAP/TAZ fusion-positive tumors (NCT04857372)." (PMID 38610930, 2024). "Multiple high potency TEADi have now been developed and subsequently entered clinical trials for cancers such as mesothelioma, as well as other cancers that harbor NF2 mutations or oncogenic YAP gene fusions." (PMID 39103676, 2024). "Mesothelioma is another cancer with NF2 driver mutations that has studies substantiating the involvement of Hippo signaling in its pathogenesis in humans." (PMID 39796693, 2024). "Another study on twelve mesothelioma cell lines indicated that cells harboring NF2 and/or LATS2 mutations were more sensitive to statins than those harboring BAP1 mutations." (PMID 38879686, 2024). "Although no consensus has been made on the specific biological pathway involved in NF2-mutant mesothelioma tumors, it is clear that NF2 mutations are characteristic of these tumors." (PMID 39796693, 2024). "In an ongoing clinical trial (NCT04665206), the first-in-class TEAD inhibitor was well tolerated with durable antitumor responses in patients with advanced mesothelioma or other cancers harboring NF2 mutations." (PMID 38493144, 2024). "NF2 mutations were, however, found in mesotheliomas as either nonsense truncating mutations or large deletions." (PMID 39796693, 2024). "Phase 1 clinical trials are currently assessing different YAP/TAZ-TEAD inhibitors in patients with mesothelioma and other cancers harboring NF2/LATS1/LATS2-mutations and tumors with functional YAP/TAZ fusions or otherwise elevated YAP/TAZ levels." (PMID 38538573, 2024). "Using the E-cadherin NF2 Hippo YAP signaling pathway as an example, E-cadherin loss-of-function causes a range of mutations in cancer, with NF2 loss-of-function mutations occurring in more than three-tenths of mesothelioma." (PMID 38469234, 2024). "The NF2 tumor suppressor gene is a frequent somatically mutated gene in mesothelioma, with 30%–40% mesotheliomas showing NF2 inactivation." (PMID 37180489, 2023). "Peritoneal mesothelioma are 10%–20% of all mesothelioma cases, and NF2 mutation is seen in 21%–35% of cases." (PMID 37180489, 2023). "Preclinical experience with a potent TEAD inhibitor, K-975, shows selective cell death in NF2-deficient mesothelioma lines." (PMID 38136262, 2023). "Recent whole-genome analysis has revealed that mesothelioma is characterized by a high frequency of mutations in a set of genes involved in the Hippo pathway, such as NF2 and LATS2." (PMID 37165917, 2023). "IAG 933, a potent inhibitor of the interaction between TEAD and the YAP/TAZ complex, is under testing in a phase I trial that is currently enrolling mesothelioma patients or patients with known NF2-inactivating mutations (NCT04857372)." (PMID 38136262, 2023). "NF2 mutation is thus thought to confer a more aggressive phenotype to mesothelioma cells, possibly involved in the induction of EMT." (PMID 37180489, 2023). "In vitro transduction of NF2 can suppress proliferation and other malignant phenotypes of NF2-deficient mesothelioma cells." (PMID 37180489, 2023). "In turn, Merlin is a critical tumor suppressor, and its inactivation by loss-of-function mutations in the NF2 gene causes NF2 syndromes such as Schwannoma, meningioma, and mesothelioma." (PMID 37337213, 2023). "NF2 deficiency has been shown to have utility as a diagnostic, prognostic, and/or predictive biomarker for mesothelioma." (PMID 37180489, 2023). "To date, mTOR inhibitors have been investigated, and an allosteric mTOR inhibitor, rapamycin, has been demonstrated to have selective growth inhibitory effects in NF2-deficient mesothelioma cells." (PMID 37180489, 2023).
mesothelioma (continued). "NF2 mutations are among the most common genetic alterations in mesothelioma, with NF2 biallelic loss being present in about 40% to 50% of tumors." (PMID 36471440, 2022). "As a result, NF2-deficient mesothelioma is exquisitely sensitive to ferroptosis induction by genetic or pharmacologic approaches." (PMID 36282248, 2022). "Mouse models showed asbestos-independent development of mesothelioma in populations with NF2 mutations." (PMID 35205798, 2022). "The anti-cancer potential of this therapeutic approach has been validated in a mesothelioma xenograft model, in which NF2-deficient cancer cells exhibited sensitivity to inhibition of TEAD palmitoylation." (PMID 35119068, 2022). "For example, loss of function mutations in the E-cadherin-NF2-Hippo pathway was frequently observed in various types of cancer including mesothelioma." (PMID 36282248, 2022). "NF2 is also mutated and deleted in mesotheliomas, clear cell renal cell carcinomas, collecting duct carcinomas of the kidney, and renal cell carcinomas with sarcomatoid dedifferentiation." (PMID 35975235, 2022). "The NF2 gene is frequently mutated in mesothelioma, ∼40% in TCGA samples and 40–60% in the literature, which is uncommon for most other cancer types." (PMID 34621176, 2021). "Following BAP1, the second most frequent mutated gene in mesothelioma is the neurofibromatosis type 2 (NF2) which encodes the protein merlin." (PMID 34249695, 2021). "There are few common mutations in mesothelioma and inactivating NF2 mutations are present in up to 60% of these tumors." (PMID 34621176, 2021). "Most importantly, we reveal that mesothelioma cells with NF2 inactivating mutations are more sensitive to quinacrine." (PMID 34621176, 2021). "In summary, we report that quinacrine has repurposing potential for mesothelioma with NF2 mutations or chemotherapy resistance, and as an adjuvant treatment." (PMID 34621176, 2021). "In previous studies, we established a series of patient-derived primary mesothelioma cell lines that have characteristics that are representative of MpM tumours with loss of NF2 (merlin) and CDKN2A32." (PMID 34389715, 2021). "The purpose of that study is to characterize the safety and tolerability of IAG933 in patients with mesothelioma, NF2/LATS1/LATS2-mutated tumors and tumors with functional YAP1/TAZ fusions, as well as to identify the maximum tolerated dose." (PMID 34685695, 2021). "In this study, we demonstrate that mesothelioma cells with inactivating NF2 mutations are more susceptible to quinacrine in vitro, but the clinical efficacy for mesothelioma tumors with inactivating NF2 mutations will need to be assessed." (PMID 34621176, 2021). "CD24 was highly expressed in human mesothelioma tissues (28/45 cases, 62%) and associated with the loss of NF2 and p16." (PMID 33298865, 2020). "Among the hyper-altered cancer types, mesotheliomas and papillary renal cell carcinomas were the most significant, and this finding was likely related to a high frequency of NF2, LATS2, and SAV1 mutations." (PMID 31959902, 2020).
mesothelioma (continued). "Roughly 40% of mesotheliomas have an NF2 mutation, causing hypophosphorylation of the YAP (Yes-Associated Protein) transcriptional coactivator." (PMID 32392897, 2020). "For instance, the somatic loss or inactivation of the NF2 gene was shown to be frequently associated with the development of isolated nervous system tumors and mesotheliomas." (PMID 32064045, 2020). "NF2 is one of the most frequently mutated genes in mesothelioma; therefore, the restoration of NF2 functions is expected to cure a large population of mesothelioma patients." (PMID 29587439, 2018). "Nf2 heterozygote background was chosen based on the fact that NF2 mutations are often observed in mesothelioma, and a previous study showing its contribution to tumor development." (PMID 29641489, 2018). "An expression analysis of 211 malignant plural mesothelioma samples suggested that among the subtypes, sarcomatoid tumors had the highest NF2 mutation rate, while epithelioid tumors had the lowest NF2 mutation rate." (PMID 29587439, 2018). "It was also shown that the restoration of NF2 expression in NF2-deficient mesothelioma cells significantly inhibited their growth." (PMID 29587439, 2018). "Further, the roles of downstream signals that are activated by NF2 loss in mesothelioma progression also remain incompletely defined." (PMID 29587439, 2018). "Recently, it was reported that mesothelioma cells with NF2 and/or LATS2 mutations were more sensitive to fluvastatin compared to those with BAP1 mutations, whereas merlin-negative breast cancer cells showed sensitivity to simvastatin." (PMID 29587439, 2018). "Mesothelioma has another frequent genetic alternations, mutations of NF2 and those of the downstream genes found in about 50% of the clinical specimens." (PMID 28464864, 2017). "A potential candidate for this approach would be the Cdkn2a gene (encoding P16Ink4a and P19ARF) that has recently been shown to genetically interact with Nf2 mutations in the development of mesothelioma." (PMID 26258444, 2015). "Deletions of chromosome arms 3p, 9p and 22q, which include the tumor suppressor genes BAP1, CDKN2A, and NF2, respectively, have all been linked to mesothelioma." (PMID 25952750, 2015). "Comparing patients 1 and 2, similarities include loss-of-function mutations in NF2, a well-characterized tumor suppressor gene that is frequently inactivated in mesotheliomas." (PMID 25798586, 2015). "NF2 somatic mutations have also been found in multiple cancer types, including but not limited to mesothelioma, anaplastic thyroid cancer, breast cancers, endometrial and liver cancers, in patients not having constitutional NF2 mutations." (PMID 24393766, 2014). "The most common cancer linked to NF2 aberrations is mesothelioma, with approximately 30-50% of tumors having mutations in the NF2 coding regio." (PMID 24393766, 2014). "NF2 is a complex gene with somatic mutations being associated with various cancers (e.g. 30 to 50 percent of mesotheliomas harbor NF2 mutations)." (PMID 24393766, 2014). "In human mesotheliomas, deletions of the Cdkn2a/Arf and Cdkn2b gene loci associated with hypermethylation are reported to be common at the NF2 gene locus." (PMID 18795165, 2008). "Notably, NF2 (neurofibromin 2), one of the most frequently mutated genes in mesothelioma, has been implicated in EMT regulation." (PMID 40277909, 2025). "It demonstrated strong antitumor efficacy in NF2-deficient mesothelioma models as monotherapy." (PMID 41347094, 2025).
mesothelioma (continued). "A recent study indicated that KRAS alterations may promote tumorigenesis in a subset of mesothelioma patients and displayed a repulsive tendency with NF2 mutations." (PMID 40707702, 2025). "The NF2 gene, located on chromosome 22q, is frequently mutated or deleted in mesothelioma." (PMID 40362535, 2025). "Prior research has shown that NF2 loss contributes to mesothelioma development." (PMID 40707702, 2025). "Indeed, we observed that H2052 mesothelioma cells carrying NF2 mutations, exhibited higher levels of CAD and DHODH compared to normal cells and other PM cell lines with wild-type NF2." (PMID 40707702, 2025). "It has been shown to block proliferation of NF2-deficient mesothelioma in vitro and in vivo." (PMID 41347094, 2025). "Moreover, statins, such as fluvastatin and simvastatin, have also been demonstrated to indirectly inhibit the activation of YAP-TEAD in NF2-deficient mesothelioma cells." (PMID 38879686, 2024). "Considering that only about 15% of mesothelioma cases show mutations in NF2, the response rate might be higher when only these patients are included." (PMID 38642130, 2024). "Genetic NF2 mutations also occur in roughly half of all mesotheliomas." (PMID 38338806, 2024). "Since BAP1 (BRCA1-Associated Protein 1) and NF2 (Neurofibromin 2) are frequently mutated in mesothelioma and exploit fundamental functions in regulating cell death, proliferation, and chromatin organization, their expression was evaluated by immunofluorescence in MSTO-211H and Met-5a cells." (PMID 39204360, 2024). "Our data point to NF2 being a cardinal sensor of mechanotransductive processes in mesothelial cells, and that the loss of NF2 therefore might play an integral part in mesothelioma during disease progress." (PMID 36740402, 2023). "In mesothelioma, due to the NF2 or LATS2 loss, Hippo signaling becomes dysregulated, although the observation of frequent subclonal NF2 mutations detected in clinical samples suggests that it may occur later in mesothelioma development." (PMID 36221913, 2022). "This is consistent with the observation of frequent subclonal NF2 mutations that may occur later in mesothelioma development." (PMID 36138075, 2022). "The unexpected discovery that mesothelioma cells with inactivating NF2 mutations are more sensitive to quinacrine may support clinical indications for the repurposing of quinacrine as an anticancer agent." (PMID 34621176, 2021). "Therefore, nonsense mutations in NF2, even those occurring close to the C-terminus, are suggested to produce functional defects and are responsible for mesothelioma development." (PMID 29587439, 2018). "The regulation of YAP and TAZ through the mevalonate pathway suggests that statins may show a more significant effect on cell growth in NF2-deficient mesothelioma and other types of tumors." (PMID 29587439, 2018). "It was shown that LATS1/2 are functional targets of CRL4DCAF1 and that in tumors with mutated NF2, such as mesothelioma, activated CRL4 induces LATS1/2 ubiquitination to promote their degradation and YAP/TAZ activation, thus stimulating oncogenesis (shown in purple)." (PMID 29587439, 2018). "In addition to a frequent loss of the 22q12 region, which is the locus of the NF2 gene, mutations within the entire NF2 coding region are common for mesothelioma." (PMID 29587439, 2018). "Allelic loss of NF2, located at 22q12.2, has been reported in up to 70 % of mesotheliomas." (PMID 27091358, 2016).